U3 (Small nucleolar RNA U3 )
Synonyms: LOC124902101
Gene: Small nucleolar RNA gene on chromosome 8 (123,180,310 to 123,180,525, reverse strand). Ensembl gene ENSG00000221461.
Gene Ontology:
Biological process: RNA processing
Cellular component: nucleolus
Homologues: Orthologues: chimpanzee U3 (99% identical), macaque U3 (93% identical). Paralogues in human: U3 (77% identical), U3 (75% identical), SNORD3P1 (75% identical), SNORD3G (75% identical), SNORD3H (74% identical), U3 (74% identical), U3 (73% identical), SNORD3E (73% identical), U3 (72% identical), SNORD3D (71% identical), U3 (71% identical), U3 (70% identical), and 12 more.